PTRHD1 (peptidyl-tRNA hydrolase domain containing 1)
Description:
As a putative peptidyl-tRNA hydrolase, it might be involved in releasing tRNAs from the ribosome during protein synthesis (Probable). Some evidence, however, suggests that it lacks peptidyl-tRNA hydrolase activity.
Synonyms: C2orf79; LOC391356; NEDPBA
Tractability: PROTAC: ubiquitination databases record sites on it; its protein half-life has been measured.
Gene: Protein-coding gene on chromosome 2 (24,789,728 to 24,793,391, reverse strand). Ensembl gene ENSG00000184924.
Subcellular location (Human Protein Atlas): Nucleoplasm
Gene Ontology:
Molecular function: protein binding; peptidyl-tRNA hydrolase activity
Cellular component: mitochondrion
Genetic constraint (gnomAD): Loss-of-function variants: 12 observed, 14.59 expected, observed/expected ratio (o/e) 0.82, 90% interval 0.53 to 1.33. The upper end of that interval is the gene's LOEUF score, 1.33, which puts it in group 5 of 6, group 1 being the genes least tolerant of losing a copy. Missense variants: 203 observed, 195.84 expected, observed/expected ratio (o/e) 1.04, 90% interval 0.92 to 1.16. Synonymous variants: 86 observed, 86.23 expected, observed/expected ratio (o/e) 1, 90% interval 0.84 to 1.19.
Homologues: Orthologues: chimpanzee PTRHD1 (100% identical), macaque PTRHD1 (99% identical), dog PTRHD1 (93% identical), mouse Ptrhd1 (89% identical), guinea pig PTRHD1 (87% identical), rat Ptrhd1 (87% identical), rabbit PTRHD1 (84% identical), tropical clawed frog ptrhd1 (59% identical), zebrafish ptrhd1 (53% identical), Drosophila melanogaster CG14903 (44% identical), Caenorhabditis elegans Y94H6A.12 (37% identical). Paralogues in human: ACP1 (18% identical).
Diseases named in the same sentence as PTRHD1 in open-access papers:
PTRHD1 is named in the same sentence as 8 diseases in open-access papers, as found by Europe PMC text mining. Sharing a sentence is not in itself a finding about the gene and the disease. The quoted sentences say what the papers report.
Parkinsonism (4 papers, 2017 to 2024). Characteristic neurologic anomaly resulting from degeneration of dopamine-generating cells in the substantia nigra, a region of the midbrain, characterized clinically by shaking, rigidity, slowness of movement and difficulty with walking and gait. "Overlapping with highly penetrant pathogenic parkinsonism genes, we identified PTRHD1 as significantly decreased in PD (FDR = 0.015), with a similar trend reported in ICICLE-PD (FDR = 0.088)." (PMID 38245550, 2024). "Two independent reports from Iran have linked PTRHD1 (C2ORF79) torecessive Parkinsonism." (PMID 28733970, 2017). "Between five and 10 patients had juvenile neuronal ceroid lipofuscinosis (JNCL), PTRHD1, RAB39B, X‐linked parkinsonism with spasticity, Alexander disease, dopa‐responsive dystonia‐parkinsonism (NR4A2), Fragile‐X syndrome or spastic paraplegia type 15 (SPG15)." (PMID 36699000, 2022).
Intellectual disability (2 papers, 2020 to 2021). "Chromosomal microdeletions encompassing the PTRHD1 gene have been previously related to many syndromes with intellectual disability." (PMID 34630269, 2021). "For example, PTRHD1:NM_001013663.1:c.365G>A;p.(Arg122Gln) was reported in 2017 in an Egyptian family with mild intellectual disability (ID) prompting the authors to propose PTRHD1 as a novel candidate gene." (PMID 33456446, 2020).
Caroli disease (1 paper, 2020). Caroli disease (CD) is a rare congenital liver disease characterized by non-obstructive cystic dilatations of the intra-hepatic and rarely extra-hepatic bile ducts. "Of note, a dual molecular diagnosis is observed in the patient 13DG0792, who is homozygous for the founder variant PTRHD1 and a ciliopathy phenotype (Caroli disease) caused by the variant WDR35 [NM_001006657.1:c.206G>A; p.(Gly69Asp)]." (PMID 33456446, 2020).
Cohen syndrome (1 paper, 2022). Cohen syndrome (CS) is a rare genetic developmental disorder characterized by microcephaly, characteristic facial features, hypotonia, non-progressive intellectual deficit, myopia and retinal dystrophy, neutropenia and truncal obesity. "The following genes were identified in 6 patients: cytogenetic band 6q21, PTRHD1, 22q11.23 deletion, Cohen syndrome, CTU2 gene, GABRA1 gene, and tuberous sclerosis." (PMID 35756865, 2022).
PTRHD1 also shares sentences with these, for which no sentence is quoted: Alexander disease (1 paper); ciliopathy (1); juvenile neuronal ceroid lipofuscinosis (1); tuberous sclerosis (1).